PADI1 (peptidyl arginine deiminase 1)
Description:
Catalyzes the deimination of arginine residues of proteins.
Synonyms: PAD1; PDI1; HPAD10; PDI
Tractability: Small molecule: a high-quality ligand is known; it belongs to a druggable protein family. PROTAC: a small molecule that binds it is known.
Target class: Enzyme; Hydrolase
Chemical probes: ML325
Gene: Protein-coding gene on chromosome 1 (17,205,128 to 17,246,007, forward strand). Ensembl gene ENSG00000142623.
Subcellular location: Cytoplasm
Subcellular location (Human Protein Atlas): Cytosol; Nucleoplasm
Pathways (Reactome):
Chromatin organization: Chromatin modifying enzymes
Gene Ontology:
Molecular function: calcium ion binding; protein binding; protein-arginine deiminase activity
Cellular component: cytoplasm; cytosol; nucleus
Genetic constraint (gnomAD): Loss-of-function variants: 54 observed, 62.33 expected, observed/expected ratio (o/e) 0.87, 90% interval 0.69 to 1.09. The upper end of that interval is the gene's LOEUF score, 1.09, which puts it in group 4 of 6, group 1 being the genes least tolerant of losing a copy. Missense variants: 852 observed, 797.37 expected, observed/expected ratio (o/e) 1.07, 90% interval 1.01 to 1.13. Synonymous variants: 348 observed, 318.35 expected, observed/expected ratio (o/e) 1.09, 90% interval 1 to 1.2.
Homologues: Orthologues: chimpanzee PADI1 (98% identical), macaque PADI1 (95% identical), pig PADI1 (83% identical), dog PADI1 (82% identical), guinea pig PADI1 (78% identical), mouse Padi1 (77% identical), rat Padi1 (76% identical), zebrafish padi2 (45% identical). Paralogues in human: PADI3 (58% identical), PADI4 (57% identical), PADI2 (52% identical), PADI6 (46% identical).
Diseases named in the same sentence as PADI1 in open-access papers:
PADI1 is named in the same sentence as 27 diseases in open-access papers, as found by Europe PMC text mining. Sharing a sentence is not in itself a finding about the gene and the disease. The quoted sentences say what the papers report.
breast carcinoma (3 papers, 2016 to 2021). "CHD4 silencing strongly stimulated PADI1 and PADI3 expression in MCF7 breast cancer cells and increased glycolysis." (PMID 33741961, 2021). "Our previous study has shown that PADI1 can regulate to function on MEK1 via citrullination and therefore affect MEK1 enzyme activity in breast cancer cells, therefore, we wondered whether PADI2 could play the similar role." (PMID 33747724, 2021).
melanoma (3 papers, 2021 to 2023). A malignant, usually aggressive tumor composed of atypical, neoplastic melanocytes. "ChIP-seq in melanoma cells revealed that CHD4 occupied an intronic regulatory element in PADI1 immediately adjacent to sites occupied by transcription factors CTCF and FOSL2 (AP1)." (PMID 33741961, 2021). "To test this idea, we grew 501Mel melanoma cells in hypoxic conditions where PADI1 and PADI3 expression was induced concomitantly with the hypoxia responsive gene VEGF." (PMID 33741961, 2021). "ONCOS-207 (which expressed tissue inhibitor of metalloprotease type 2 [TIMP2]), ONCOS-209 (which expressed peptidyl arginine deiminase [PADI1]), and ONCOS-210 and ONCOS-212 (which expressed both TIMP2 and PADI1) exhibited oncolytic activity against four melanoma cell lines in vitro." (PMID 36816748, 2023). "In this study, our four novel oncolytic adenoviruses armed to express one or both PADI1 and TIMP2 exhibited varied levels of cytotoxicity against four melanoma cell lines in vitro in a dose-dependent manner." (PMID 36816748, 2023). "In contrast, expression of PADI1 and PADI3 was strongly induced in all tested melanoma lines." (PMID 33741961, 2021). "As these four melanoma cells did not express ASS1 they might be more sensitive to arginine deprivation induced by local expression of PADI1." (PMID 36816748, 2023). "Analyses of the Cancer Cell Line Encyclopaedia (CCLE) showed a strong correlation of PADI1 and PADI3 expression indicating their co-regulation was not restricted to melanoma cells." (PMID 33741961, 2021).
clear cell renal carcinoma (2 papers, 2021 to 2023). A malignant epithelial neoplasm of the kidney characterized by the presence of lipid-containing clear cells within a vascular network. "Interrogation of the TCGA showed PADI1 and/or PADI3 expression in several solid tumours, bladder, pancreatic, cervical, head and neck and clear cell renal cancers with known hypoxic character." (PMID 33741961, 2021).
colorectal cancer (2 papers, 2022 to 2025). A primary or metastatic malignant neoplasm that affects the colon or rectum. "Finally, we used the colorectal cancer microarray in the TCGA database to map 11 genes in which PADI1 was associated (p < 0.05)." (PMID 36471887, 2022). "In the last five years, a growing body of research has identified PADI1 and its involvement in multiple cancers including pancreatic ductal adenocarcinoma, colorectal cancer, nasopharyngeal carcinoma and several squamous cell carcinomas." (PMID 41327336, 2025). "Genes from PADI1-related co-expression as a newly developed signature show great potential as prognostic biomarkers and immunotherapy predictors in colorectal cancer patients." (PMID 36471887, 2022). "In this study, we analyzed the differential expression of PADI1 in colorectal cancer (CRC)." (PMID 36471887, 2022).
nasopharyngeal carcinoma (2 papers, 2023 to 2025). A carcinoma arising from the nasopharyngeal epithelium. "PADI1 can also mediate the proliferation, metastasis and cisplatin resistance of nasopharyngeal carcinoma (NPC) through the TINCR-ALY-PADI1-MAPK-MMP2/9 axis." (PMID 37020554, 2023).
chickenpox (1 paper, 2020). A contagious childhood disorder caused by the varicella zoster virus. "The high levels of PADI1 observed here in the SARS-CoV-2 skin biopsies may possibly contribute to some of the cutaneous manifestations related to COVID-19, which include an erythematous rash, urticarial, chickenpox-like vesicles, acral lesions (“COVID toes”) and livedoid lesions." (PMID 32629995, 2020).
cutaneous melanoma (1 paper, 2021). A primary melanoma arising from atypical melanocytes in the skin. "Analyses of TCGA human tumour datasets showed strongly positively correlated co-expression of PADI1 and PADI3 in multiple tumour types such as cutaneous melanoma, uveal melanoma, bladder, lung and head and neck, with PADI1 often being the gene showing strongest correlation with PADI3." (PMID 33741961, 2021).
diabetic retinopathy (1 paper, 2018). "This region spans genes with plausible roles in the development of diabetic retinopathy, (e.g. PADI1, PADI2, PADI3, and PADI4, as well as genes known to be involved in kidney function (CLCNKA and CLCNKB)." (PMID 29444168, 2018).
lung adenocarcinoma (1 paper, 2021). A carcinoma that arises from the lung and is characterized by the presence of malignant glandular epithelial cells. "In pancreatic adenocarcinoma, ccRCC, and lung adenocarcinoma, PADI1 and PADI3 expression was positively correlated with the hypoxic signature of the different patient samples." (PMID 33741961, 2021).
lymph node metastasis (1 paper, 2022). "To further clarify the survival prognosis differences of PADI1 in different clinical features of CRC, we observed the survival differences of PADI1 by six clinical features, namely, age, gender, tumor size, lymph node metastasis, distant metastasis, and TNM stage, respectively." (PMID 36471887, 2022).
rheumatoid arthritis (1 paper, 2012). A chronic, systemic autoimmune disorder characterized by inflammation in the synovial membranes and articular surfaces. "A total of 320 SNPs from the PADI locus (including PADI1, PADI2, PADI3, PADI4 and PADI6 genes) were genotyped in 1,238 RA cases and 1,571 control subjects from the Malaysian Epidemiological Investigation of Rheumatoid Arthritis (MyEIRA) case-control study." (PMID 23164236, 2012).
cancer (13 papers, 2021 to 2025). A tumor composed of atypical neoplastic, often pleomorphic cells that invade other tissues. "We found that two risk genes, DPY30 and PADI1, were significantly positively associated with several identified cancer-related genes." (PMID 34090418, 2021). "However, while a growing number of researches have shown that PADI-mediated histone citrullination is highly associated with cancer development, PADI1 has been the one that is overlooked." (PMID 34090418, 2021). "The citrullination of Arg 10 in PKM2 by PADI1 can lead to an increase in glycolysis, thus promoting the proliferation of cancer cells." (PMID 37020554, 2023). "The reduced anti-cancer effect (ability to control the tumor growth) observed in mice treated with ONCOS-210 (2.5 × 106 VP/tumor treatment) might be related to lower expression of encoded transgene such as PADI1, which presumably relates to low virus dose used in the study (2.5 × 106 VP/tumor)." (PMID 36816748, 2023). "We first observed the difference in mRNA expression levels of PADI1 in pan-cancer, and the TIMER database showed that PADI1 was expressed at high and at low to medium levels." (PMID 36471887, 2022). "In human cancers, PADI1 and PADI3 expression is regulated by hypoxia stimulating PKM2 activity and contributing to the increased glycolysis seen under hypoxic conditions." (PMID 33741961, 2021). "We examined the correlation between the hypoxic signatures of several cancer types with PADI1 and PADI3 expression." (PMID 33741961, 2021). "This correlation was lower in cancers, such as bladder orf cervical that had higher intrinsic PADI1 and PADI3 expression." (PMID 33741961, 2021). "CHD4 induces PADI1 and PADI3, causing pyruvate kinase isozyme M2 (PKM2) R106 citrullination that enhances serine activation, sustaining glycolysis under hypoxia and reshaping cancer cell proliferation." (PMID 41562091, 2025). "Although the role of PADI1 in cancer progression has also been elucidated, and PADI1-mediated histone citrullination is crucial in early embryonic development, it remains to be explored whether PADI1-mediated histone citrullination play a role in cancer development." (PMID 34090418, 2021). "The four histone modification-related genes highlighted, including DPY30, CBX8, CENPT, and PADI1, have been reported to have the potential to regulate the occurrence and development of cancer to some extent by altering the histone modification of cancer-related genes." (PMID 34090418, 2021). "In cancer, PADI1 can promote tumor proliferation, migration, invasion and drug resistance by promoting energy metabolism and signal transduction (MEK1-ERK1/2-MMP2, ERK1/2-p38 and PADI1-MAPK-MMP2/9), thus it acts as oncogene in cancer." (PMID 37020554, 2023). "PADI1 and PADI3 can promote glycolysis through citrulline pyruvate kinase M2 (PKM2) arginine 106, leading to the proliferation of cancer cells." (PMID 37020554, 2023). "Here, the authors show that PKM2 citrullination by PADI1 and PADI3 lowers its sensitivity to metabolic inhibitors leading to increased glycolysis and reduced cancer cell proliferation." (PMID 33741961, 2021). "PADI1 and PADI3 were co-ordinately regulated in multiple types of cancer cells and their expression was inversely related to that of CHD4." (PMID 33741961, 2021). "Here we show that CHD4 regulates expression of PADI1 (Protein Arginine Deiminase 1) and PADI3 in multiple cancer cell types modulating citrullination of arginine residues of the allosterically-regulated glycolytic enzyme pyruvate kinase M2 (PKM2)." (PMID 33741961, 2021). "There were no researches about the roles of FUT7, PADI1, PPL, and ARHGAP40 in LSCC, but the roles of these genes or the related genes in other cancers were reported." (PMID 34131588, 2021).
tumor (10 papers, 2012 to 2023). "Indeed, the immune score was higher in the low-risk group of PCGs, which may be related to the fact that PADI1 has been reported to have an immunosuppressive function, an ability that the tumor may exploit to promote its ability to escape immune cells." (PMID 36471887, 2022). "Local expression of peptidyl arginine deiminase type I (PADI1) in tumors can provide enhanced tumor apoptosis, antiangiogenic effects, and reduced production of nitric oxide induced by arginine deprivation." (PMID 36816748, 2023). "Dual-expressing (TIMP2 + PADI1) oncolytic adenoviruses had significantly higher anti-tumor activity than single-transgene oncolytic viruses and vehicle control." (PMID 36816748, 2023). "First, PADI1 can affect the proliferation of tumor cells by participating in energy metabolism." (PMID 37020554, 2023). "In several human tumours, PADI1 and PADI3 expression was positively correlated with hypoxia." (PMID 33741961, 2021). "Among the five genes in ccRCC, ATP6V0D2, DPP6, PADI1 and PLG were significantly associated with AJCC-stage (p < 0.05); ATP6V0D2, C9orf135, DPP6 and PLG were significantly associated with nodal metastasis (p < 0.05); ATP6V0D2, DPP6 and PLG were significantly associated with tumor grade (p < 0.05)." (PMID 32002016, 2020). "Among them, DPY30, EREG, PLA2G16, ZNF185, PADI1, INPP4B and AP1S3 have been reported to be involved in tumor genesis and progression, and they were significantly positively correlated with risk score." (PMID 34090418, 2021). "Herein, we found that 5 genes (Shisa3, PADI1, LRP2, ANGPTL4 and ALOX15B) were upregulated and 4 genes (CXCL9, ADAMDEC1, SCGB1A1/CC10, HLA-G) were downregulated in PR tumor tissues compared to SD tumor tissues." (PMID 31801598, 2019). "The ONCOS-210 and ONCOS-212 oncolytic adenoviruses, which express both PADI1 and TIMP2, and the combination (ONCOS-207 + ONCOS-209) significantly inhibited A2058 tumor growth in the nude mouse model compared with the vehicle-treated group and the single-transgene vectors ONCOS-207 and ONCOS-209." (PMID 36816748, 2023). "Despite this strong co-regulation, no negative correlation with CHD4. was seen suggesting there may be alternative mechanisms regulating PADI1 and PADI3 co-expression in tumours." (PMID 33741961, 2021).
infection (2 papers, 2019 to 2023). The state of being infected such as from the introduction of a foreign agent such as serum, vaccine, antigenic substance or organism. "ONCOS-210 had the expression cassette PADI1-P2A-TIMP-2, whereas ONCOS-212 used the CMV promoter to provide constitutive expression of the two transgenes throughout infection: CMV promoter-PADI1-IRES-TIMP-2-SV40 poly A signal." (PMID 36816748, 2023).
adenocarcinoma (1 paper, 2020). A common cancer characterized by the presence of malignant glandular cells. "In vitro lung epithelial and adenocarcinoma alveolar cell models revealed that PADI1, PADI2 and PADI4 mRNA levels were elevated, but PADI3 and PADI6 mRNA levels were reduced in SARS-CoV-2-infected NHBE cells." (PMID 32629995, 2020).
PADI1 also shares sentences with these, for which no sentence is quoted: pancreatic cancer (2 papers); atherosclerosis (1); COVID-19 (1); glioma (1); laryngeal squamous cell carcinoma (1); lung carcinoma (1); pancreatic adenocarcinoma (1); pancreatic ductal adenocarcinoma (1); squamous cell carcinoma (1); thyroid autoimmunity (1); uveal melanoma (1); virus infection (1).